CRP (C-reactive protein)
Diseases named in the same sentence as CRP in open-access papers (continued):
Sharing a sentence is not in itself a finding about the gene and the disease.
chronic kidney disease (continued). "We studied the association of inflammatory biomarkers including C-reactive protein (CRP), tumor necrosis factor-alpha (TNF-α), and interleukin-6 (IL-6) with chronic kidney disease (CKD)." (PMID 26025192, 2015). "However, when subjects with reduced renal function were excluded from the analysis, only sTNF-R1 and Interleukin 6 (IL-6), but not CRP, remained positively associated with incident chronic kidney disease." (PMID 25259714, 2014). "In patients with chronic kidney disease (CKD), lowering uric acid has been reported to significantly improve CRP levels, independently slow the progression of renal disease, and reduce cardiovascular events by 71%." (PMID 28352421, 2013). "Elevated plasma SDMA levels were found to correlate with inflammatory markers, such as TNF-alpha, high sensitivity CRP and Interleukin-6 (IL-6) in chronic kidney disease (CKD) patients." (PMID 23443106, 2012). "Age, history of cardiomyopathy, severe chronic renal failure, serum PTH concentration, serum CRP concentration and use of systemic corticosteroids were associated with 2 year mortality in unadjusted model but not in the fully-adjusted model." (PMID 40882292, 2025). "This study investigated the association between the C-reactive protein-albumin-lymphocyte (CALLY) index and all-cause mortality and cardiovascular disease (CVD) mortality in patients with chronic kidney disease(CKD) while exploring biological aging as a potential mediator." (PMID 41254862, 2025). "Age, history of cardiomyopathy, severe chronic renal failure, serum PTH concentration, serum CRP concentration and use of systemic corticosteroids were associated with 6-months mortality in unadjusted model but not in the fully-adjusted model." (PMID 40882292, 2025). "In patients with chronic kidney disease (CKD), a common complication of T2D, elevated CRP levels have been shown to inversely correlate with glomerular filtration rate, suggesting its utility for monitoring renal function." (PMID 40004236, 2025). "It aims to explore the efficacy of ziltivekimab, administered subcutaneously once a month for 4 years, in reducing MACE in patients with chronic kidney disease (CKD), elevated CRP, and evidence of atherosclerotic cardiovascular disease." (PMID 39404934, 2024). "The Second Manifestations of Arterial Disease 2 (SMART2) model, intended for individuals with a previous CVD event, also considers chronic kidney disease (CKD) and high-sensitivity C-reactive protein (CRP) levels to predict future events in addition to the standard factors." (PMID 39200741, 2024). "ROS contribute to tissue inflammation with increased levels of inflammatory mediators, including IL-6, C-reactive protein (CRP) and TNF, which are detected in both acute and chronic kidney disease and acute and chronic HF." (PMID 36982164, 2023). "NLR, Neutrophil-lymphocyte ratio; CRP, C-reactive protein; CKD, chronic kidney disease; CT, computed tomography; eGFR, estimated glomerular filtration rate." (PMID 35103220, 2022). "According to estimations, more than 30%–50% of patients with end-stage renal disease (ESRD) have serological evidence of an active inflammatory state, such as elevated levels of CRP and pro-inflammatory cytokines." (PMID 35690731, 2022). "FGF23 upregulates interleukin (IL)-6 and C-reactive protein (CRP) expression in the liver, thereby promoting inflammation in chronic kidney disease." (PMID 35084563, 2022). "We found that CRP level increased progressively with CKD stage; this is in line with the findings of epidemiological studies, the Chronic Renal Insufficiency Cohort, and the Cardiovascular Health Study." (PMID 35433774, 2022). "In a study that included 30 patients with end-stage renal disease (ESRD), the gut bacterial DNA was detected in the blood of 20% of patients with higher levels of C-reactive protein (CRP) and IL-6 than detected in the remaining studied patients." (PMID 36583819, 2022).
chronic kidney disease (continued). "Effects of Shenkang injection (SKI) on the levels of CRP, IL-1β, IL-6, TNF-α, IL-4,and IL-10 in serum of chronic renal failure rats*." (PMID 35674582, 2022). "If the CRP value was increased, the adherence of monocytes to the formed biofilm was especially high in case of ADPKD and chronic kidney disease." (PMID 34580787, 2021). "In a prospective randomized trial of patients with chronic kidney disease (CKD) (eGFR < 60 mL/min/m2), administration of allopurinol for 24 months decreased CRP and slowed the progression of CKD." (PMID 34830282, 2021). "Preoperative prognostic factors include the presence of hydronephrosis, serum CRP, tumor size, tumor location, history of previous bladder cancer, age, Eastern Cooperative Oncology Group performance status (ECOG PS), and chronic kidney disease (CKD)." (PMID 34575266, 2021). "A1AG, Alpha-1 acid glycoprotein; CRP, C-reactive protein; eGFR, estimated glomerular filtration rate; ESRD, end-stage renal disease; IVC, inferior vena cava; MHD, maintenance hemodialysis; pro-BNP, Pro-brain natriuretic peptide; PH, pulmonary hypertension." (PMID 33816034, 2021). "Of note, Sub2 contained ICU patients (n = 16) with the lowest CRP levels, SOFA- and WHO scores but highest PF ratios and with the longest disease durations (DASO) plus one deceased patient with chronic renal failure after renal transplantation." (PMID 34893580, 2021). "Chronic inflammatory states are commonly found in patients with end-stage renal disease, and inflammatory cytokines, including IL-6, IL-1, TNF-a and CRP play an important role." (PMID 33413177, 2021). "We clarified the impact of the preoperative CRP/albumin ratio on AKI and evaluated the impact of postoperative AKI on end-stage renal disease (ESRD) among elderly cystectomy patients." (PMID 33193910, 2020). "Patients with greater age, severe dementia, chronic kidney disease, lower serum albumin, TLC, TC, and hemoglobin levels, as well as higher C-reactive protein levels were more likely to receive TPN." (PMID 31577813, 2019). "For example, hs-CRP levels were not considerably different between APOE genotype carriers in Moroccan patients with end-stage renal disease (ESRD), and, in our study, some ε4 carriers exhibited high CRP levels." (PMID 27177774, 2016). "The five blood biomarkers investigated were PCT, CRP, WBC, ProADM, and copeptin, and the six pre-analytic factors were antibiotic or steroid pretreatment, age, gender, chronic renal failure, and chronic liver insufficiency." (PMID 25419180, 2014). "Compared with healthy controls and end-stage renal disease patients on maintenance hemodialysis or peritoneal dialysis, patients with AKI had significantly higher levels of CRP/prealbumin (p < 0.001)." (PMID 21714897, 2011). "Chronic kidney disease is characterized by a persistent state of low-grade inflammation driven by elevated cytokines such as interleukin-6 (IL-6), tumor necrosis factor-α (TNF-α), and C-reactive protein (CRP)." (PMID 41552179, 2025). "Potential of this IL‐6 inhibitor in reduction of CRP and MACE rates amongst patients with cardiovascular disease, chronic kidney disease and baseline hs‐CRP levels of > 2.0 mg/L, is currently being tested in the ZEUS trial; results of which are highly anticipated." (PMID 40309624, 2025). "Backgrounds of patients with inflammatory mucosa included high CRP, use of nonsteroidal anti-inflammatory medications, chronic renal failure, and cancer." (PMID 40230560, 2025). "Routine blood investigations showing negative procalcitonin, improving CRP following drainage of malignant pleural effusion without antibiotic treatment, and stable chronic kidney disease parameters." (PMID 40922881, 2025).
chronic kidney disease (continued). "Chronic kidney disease, malignancy, CRKP strain infection, recent ICU admission, bloodstream infection, urinary tract infection, respiratory tract infection, C-reactive protein level, creatinine level, and SOFA score were significant factors for 90-day mortality in the univariate analysis." (PMID 38534717, 2024). "However, they had a lower proportion of Caucasians, lower counts of neutrophils (NEU), C-reactive protein (CRP), CLR, NPAR, NLR, SII, and lower prevalence of chronic kidney disease and cancer, indicating lower risks of cardiovascular and all-cause mortality." (PMID 39726875, 2024). "Observational studies have shown that low-grade inflammation, as assessed by highly sensitive C-reactive protein (CRP), was highly predictive of cardiovascular disease (CVD) in the general population, advanced chronic kidney disease patients and dialysis-dependent patients." (PMID 38034546, 2023). "In the pre-dialysis population, the Chronic Renal Insufficiency Cohort study including 3,875 patients with stages II–IV CKD revealed that the elevation of inflammatory parameters, such as CRP, IL-6, and fibroblast growth factor 23, were independent predictive factors for mortality." (PMID 37974082, 2023). "Multivariate logistic regression analysis revealed old age, low BMI, chronic kidney disease, drug-resistant TB, high CRP levels, and the absence of hyperuricemia as factors associated with death during TB treatment." (PMID 37972037, 2023). "In patients with chronic kidney disease (CKD), the severe storm of metabolic dysfunction results in fewer calcification inhibitors and a higher proportion of calcification-related markers such as Gla-rich proteins (CRP) in MVs, which accelerates the calcification of the intima and media." (PMID 35585052, 2022). "In addition, the levels of blood markers (urea, creatinine, uric, CRP and MDA) increased considerably with advancing stages of chronic renal failure." (PMID 34529688, 2021). "A study showed that patients with chronic kidney disease with lower eGFR levels had higher levels of plasma IL-1 β, IL-1RA, IL-6, TNF-α, hypersensitive CRP, and fibrinogen and that the inflammation score was inverted with GFR estimates and urinary albumin/creatinine ratio (UACR)." (PMID 34992536, 2021). "Blood analysis showed a digitalis intoxication, a slightly elevated C-reactive protein without leucocytosis and discrete hypoalbuminemia and a grade 2 chronic kidney disease (CKD-epi)." (PMID 32143640, 2020). "The Chronic Renal Insufficiency Cohort (CRIC) study found an inverse correlation between renal function and inflammatory biomarkers (IL-1β, IL-1 receptor antagonist, IL-6, TNF-α, C-reactive protein, and fibrinogen) as well as a direct relationship between kidney disease and albuminuria." (PMID 32823917, 2020). "Chronic kidney disease (CKD) is a state of chronic, low-grade inflammation which contributes to the accelerated progression of chronic inflammatory disturbances affecting immune balance with increased levels of innate immunity biomarkers, such as C-reactive protein (CRP) and interleukin (IL)-6." (PMID 32290429, 2020). "A recent study even added to the fact that elevated urine albumin and high CRP could increase value to MetS variables in predicting CVD and chronic kidney disease." (PMID 24835219, 2014). "MCV: mean corpuscular volume; eGFR CKD-EPI refers to the estimated glomerular filtration rate calculated using the Chronic Kidney Disease Epidemiology Collaboration (CKD-EPI) equation; CRP: C-reactive protein." (PMID 41458829, 2025). "MCV: mean corpuscular volume, eGFR: estimated glomerular filtration rate, CKD-EPI: chronic kidney disease epidemiology collaboration, ALP: alkaline phosphatase, CRP: C-reactive protein." (PMID 41147027, 2025). "CKD, chronic kidney disease; COPD, chronic obstructive pulmonary disease; CRP, C-reactive protein; CT, computed tomography." (PMID 39897284, 2025).
chronic kidney disease (continued). "In addition, elevated levels of inflammatory markers, interleukin-6 (IL-6), tumor necrosis factor-alpha (TNF-α), and C-reactive protein (CRP) in patients with chronic kidney disease (CKD) may induce oxidative stress, thereby accelerating the progression of renal damage." (PMID 38004033, 2023). "Common comorbidities, including obesity, diabetes, hypertension, chronic obstructive pulmonary disease (COPD), and chronic kidney disease (CKD), have been postulated to drive the systemic inflammatory state, as shown by elevated levels of circulating cytokines, including IL-1β, IL-6, CRP, and TNFα." (PMID 36818566, 2023). "In this meta-analysis of patient cohorts with CRP levels ranging, on average, from 2.2 mg/L to 13.4 mg/L, supplementation with ALA reduced CRP levels by 1.3 mg/L, arguing for an anti-inflammatory effect of ALA supplementation in patients with chronic kidney disease." (PMID 37047085, 2023). "Chronic kidney disease > stage 2, CRP at admission, and dialysis treatment were not predictors." (PMID 36555328, 2022). "In the Chronic Renal Insufficiency Cohort (CRIC) study, an inverse relationship between biomarkers of inflammation (interleukin-1β, interleukin-1 receptor antagonist, interleukin-6, tumor necrosis factor-α, C-reactive protein, and fibrinogen) and renal function was advocated." (PMID 33466271, 2021). "In another clinical study 43 patients with end stage renal disease (ESRD) were separated into either the control group or the inflamed group based on their plasma C-reactive protein (CRP) levels; a control (CRP < 3.0 mg/L) and an inflamed group (CRP ≥ 3.0 mg/L)." (PMID 33503867, 2021). "In addition to CRP, serum albumin correlates with LTM in chronic kidney disease patients." (PMID 32824951, 2020). "Interestingly, patients with chronic kidney disease who require high‐dose erythropoietin were found to have higher levels of circulating pro‐inflammatory biomarkers IL6 and CRP that may translate to higher levels of VTE." (PMID 35847693, 2020). "Lower heart rate variability was significantly associated with older age, female gender, diabetes, higher heart rate, C-reactive protein and phosphorus, lower serum albumin, higher high-density lipoprotein, and stage 5 chronic kidney disease in patients with nondialysis chronic kidney disease." (PMID 24982887, 2014). "Furthermore, the direct association between abundance of Prevotellaceae and some toxic molecules in serum has been found in patients with end stage renal disease, however, these toxic molecules are indoxyl sulfate, p-cresol, and C-reactive protein, rather than serum urate." (PMID 37468996, 2023). "In a study on a chronic renal insufficiency cohort (CRIC) without DM, a multivariable-adjusted analysis showed many independent factors associated with a higher HOMA-IR, including age, no-smoking, BMI, waist circumference, hemoglobin, LDL, HDL, triglyceride, and C-reactive protein." (PMID 35889789, 2022). "Fourth, Inflammation.In patients with chronic kidney disease, an independent negative correlation between inflammatory cytokines (TNF-α, IL-6 and CRP) and FT3 was found." (PMID 37821807, 2023). "The further explorative adjustment for chronic kidney disease by means of CKD-EPI (which did not qualify to the main model 2, considered our main model) in model 3 decreased the HRs for SUA and CRP." (PMID 23029307, 2012).
periodontitis (494 papers, 2007 to 2026). An acute or chronic inflammatory process that affects the tissues that surround and support the teeth. "The previous study elucidated that the C-reactive protein (CRP)/bone morphogenetic protein 4 (BMP4) signaling pathway mediates periodontitis-associated anxiety-like behaviors in rats." (PMID 42318640, 2026). "The association of dietary indices and advanced periodontitis with serum CRP levels after 11 years of follow-up was analyzed with linear regression." (PMID 41982490, 2026). "This study aimed to evaluate the combined association of diet and advanced periodontitis with serum high-sensitivity C-reactive protein (hs-CRP) levels at baseline and after 11 years." (PMID 41982490, 2026). "Another cross-sectional study involving 70 participants found that serum high-sensitivity CRP and fibrinogen levels were correlated with the severity of periodontitis, with the association strengthening as the severity of periodontal disease increases." (PMID 40862144, 2025). "Elevated CRP levels have been independently associated with both periodontitis and cardiovascular events, reinforcing the inflammation-driven model of CVD." (PMID 41007869, 2025). "One study also provides evidence that the association between periodontitis parameters reflecting inflammation and high/uncontrolled blood pressure (≥130/80 mmHg) is mediated by inflammatory markers such as CRP, white blood cells, and ferritin." (PMID 40572711, 2025). "Elevated inflammatory markers associated with periodontitis, such as C-reactive protein and interleukins, have been linked to worsening renal function." (PMID 40566124, 2025). "Periodontitis, the leading cause of adult tooth loss, triggers chronic low-grade inflammation, marked by elevated levels of interleukin-6 (IL-6) and C-reactive protein (CRP), two biomarkers consistently linked to frailty, sarcopenia, and functional impairment." (PMID 41398005, 2025). "After adjustment for age, smoking, and BMI, CRP levels were 1.7 times higher in individuals with periodontitis, indicating the association persists beyond key confounders." (PMID 41301163, 2025). "Biomarkers such as cytokines, matrix metalloproteinases (MMPs), and C-reactive protein (CRP) have been reported to reflect the inflammatory state associated with periodontitis." (PMID 40002815, 2025). "The present study builds upon these findings, demonstrating that elevated CRP levels are significantly associated with an increased risk of periodontitis." (PMID 39859455, 2025). "CRP and eGFR emerged as potential biomarkers for predicting periodontitis, enabling early interventions to prevent tooth loss and systemic complications." (PMID 39859455, 2025). "This study explored systemic and oral health indicators, including CRP and eGFR, as potential factors associated with periodontitis, using a longitudinal clinical dataset comprising 23,742 records from patients identified by ICD-10 codes between 2015 and 2022." (PMID 39859455, 2025). "The advent of novel technologies capable of detecting CRP in saliva underscores its potential as a diagnostic instrument for various oral inflammatory and immune conditions, including periodontitis and HNC, given the non-invasive nature of saliva collection." (PMID 40076898, 2025). "In response to elevated PGE, TNF-α, IL-1 and IL-6, periodontitis causes the liver to produce more CRP, especially in early pregnancy." (PMID 41394354, 2025). "Despite accounting for confounding factors such as smoking, studies consistently show significant associations between serum levels of CRP and IL-6 and periodontitis." (PMID 40136726, 2025). "Repeatedly elevated inflammatory markers, including IL-6, TNF-α, and CRP, as well as regulatory T-cells, were observed in individuals with periodontitis, indicating a potentially shared pathogenic environment with certain tumors." (PMID 41384174, 2025).